IL6 (interleukin 6)
Diseases named in the same sentence as IL6 in open-access papers (continued):
Sharing a sentence is not in itself a finding about the gene and the disease.
depression (continued). "Patients with depression often exhibit increased levels of interleukin-6 (IL-6), IL-1β, IL-10, tumour necrosis factor-α (TNF-α), CRP, and transforming growth factor-β (TGF-β), many of which are produced in response to cellular stress through inflammasome activation." (PMID 41226736, 2025). "The inflammatory hypothesis of depression hypothesizes that elevated IL-6 levels contribute to the pathophysiology of depression by disrupting neurotransmitter systems and promoting neuroinflammation." (PMID 40305200, 2025). "In this model, depression-like behaviors correlate with the release of pro-inflammatory cytokines, including interleukin 1β (IL1β), interleukin 6 (IL6), and tumor necrosis factor α (TNFα), in both the brain and plasma, thereby establishing a connection between inflammation and depressive symptoms." (PMID 40001487, 2025). "After the first step of adjustment (for age and gender), TNF-α and IL-6 levels were no longer significantly associated with depression." (PMID 39922907, 2025). "Most studies, including our initial findings, confirm elevated CRP and IL-6 levels in depression." (PMID 40428308, 2025). "•Serotonin, cortisol, IL-6, and NF-kB in the brain affect depression-like behavior." (PMID 39911318, 2025). "The acute and chronic stress, and the possible long-term neuroinflammation faced by PLWH may lead to higher circulating levels of IL-6, making these individuals much more susceptible to the development of HIV-associated depression." (PMID 40313235, 2025). "The pathogenesis of depression in numerous psychiatric disorders is characterized by chronic inflammation, which is associated with elevated levels of proinflammatory cytokines (such as TNF and IL-6)." (PMID 41463013, 2025). "Available research demonstrates that schizophrenia and depression both have shown increased rates of cytokines, including IL-1β, IL-6, and TNF-α, which indicate systemic inflammation followed by cognitive impairment, treatment unresponsiveness, and disturbances in mood." (PMID 40416228, 2025). "Previous study demonstrated that intracerebroventricular administration of IL-6 induces depression-like behavior by activating STAT3-dependent regulation of serotonin transporter function, highlighting the interplay between IL-6 elevation and STAT3 signaling in mood dysregulation." (PMID 41428145, 2025). "One of the most studied proinflammatory cytokines related to depression is IL-6." (PMID 40305200, 2025). "Similar findings have been reported elsewhere, showing that IL-6 associates with more severe depression in female but not male adolescents." (PMID 39865800, 2025). "Research has demonstrated that vagus nerve stimulation can ameliorate depression-like behaviors brought on by SD by lowering the levels of interleukin-1β (IL-1β) and interleukin-6 (IL-6) in peripheral blood and the hippocampus, as well as by preventing astrocyte and microglia activation." (PMID 40395724, 2025). "Identification of the cellular source of proinflammatory IL-6 may facilitate future therapies for psychiatric disorders like depression, eating disorders, or PTSD —all of which show elevated circulating levels of IL-6." (PMID 41450979, 2025). "In particular, individuals with poor emotional regulation or low sleep quality were more vulnerable to the negative effects of elevated inflammatory markers, such as CRP, IL-6, and TNF-α, associated with greater fatigue, somatic complaints, depression, and anxiety." (PMID 41333345, 2025). "Additionally, MAZ51 led to a decrease in the protein levels of PSD95 as well in the hippocampus, which was paralleled by an elevation in TNF-α and IL-6 levels, and aggravated depression-like behavior." (PMID 40809378, 2025). "Notably, alterations in IL-6 serum levels are among the most reproducible abnormalities in depression patients." (PMID 39864626, 2025).
depression (continued). "Specifically, higher peripheral IL-6 levels prior to the onset of the first episode of psychosis or depression and before treatment initiation suggest that increased peripheral IL-6 levels may be associated with the onset of psychotic and depressive symptoms." (PMID 39911538, 2025). "More direct evidence of the relationship between inflammation and depression has been demonstrated by an increase in interleukin-6 (IL-6), C-reactive protein (CRP), and tumor necrosis factor-alpha (TNF-α) associated with a higher risk of depression and increased symptoms." (PMID 41333345, 2025). "In another clinical research published in Cytokine in 2001, Kudoh and collaborators investigated the inflammatory cytokine response of patients with chronic depression during abdominal surgery and found that the response of IL-6 to surgical trauma depended on the clinical state of depression." (PMID 39791171, 2025). "Yet, interestingly regarding IL-6 levels, patients 1 and 2 with the highest levels and the highest depression scores, showed clear reductions after eight weeks treatment; patient 1 showed a reduction of IL-6 from 5.9 to 4.7 pg/L and patient 2 from 11.0 to 7.3 pg/L." (PMID 39867848, 2025). "Nonetheless, when combined with other salivary biomarkers such as cortisol or alpha-amylase, IL-6 may enhance the predictive accuracy of psychophysiological models used to detect and monitor anxiety, depression, and stress-related disorders." (PMID 40728957, 2025). "Chronic airway inflammation in active asthma may exacerbate neuroinflammation, disrupt hypothalamic-pituitary-adrenal (HPA) axis activity, and elevate pro-inflammatory cytokines such as IL-6, which are known to be involved in depression and impulsivity." (PMID 40460338, 2025). "In order to determine a potential association between the altered IL-6 serum level after BLT and the improvement in depression symptoms, participants were divided into those who responded well, i.e., responders, and those who did not respond well, i.e., non-responders, to BLT." (PMID 40001598, 2025). "On the one hand, sleep disorders could lead to an increase in inflammation, and the elevated levels of inflammatory markers CRP and IL-6 could increase the prevalence of depression symptoms." (PMID 40688961, 2025). "Given that numerous studies suggest the IL‐6 trans‐signaling pathway may contribute to depression, we treated the CSDS mice with sgp130, an inhibitor of this pathway." (PMID 39888279, 2025). "It is important to highlight that growing evidence indicates a potential link between depression and systemic inflammation, particularly the presence of IL-6, which may contribute to the exacerbation of depressive symptoms." (PMID 40852367, 2025). "TB infection can also trigger the release of pro-inflammatory cytokines, such as Interleukin-6 (IL-6), which may contribute to depression." (PMID 40136579, 2025). "The study's limitations include a small sample size of UC patients, the lack of analysis of gut microbiota composition and fecal butyrate levels, and the omission of key inflammatory cytokines such as IL-6 and TNF-α as well as some potential diagnostic biomarkers for depression such as BDNF." (PMID 40123849, 2025). "The authors found that symptoms experienced by patients with incurable cancer—most often, depression, fatigue, pain, and lack of appetite—were associated with circulating cytokines such as IL-6, interleukin 8, and tumor necrosis factor-alpha, among others." (PMID 39996862, 2025). "Decreased IL-1β and increased IL-6 may act as a compensatory mechanism in depression to counter act dysregulated neuroinflammatory response." (PMID 40179065, 2025). "Presurgical high‐intensity interval training (HIIT) may improve tumor proliferation (Ki67), body composition, VO2peak, IL‐6, and depression in breast cancer patients." (PMID 40859620, 2025).
depression (continued). "IL-6 inhibitors (e.g., tocilizumab) have shown promise in reducing systemic inflammation and improving mood symptoms, particularly in patients with treatment-resistant depression." (PMID 40218134, 2025). "Both excessively high and excessively low levels of IL-6 may contribute to mental health problems, such as depression, anxiety, and schizophrenia." (PMID 41274868, 2025). "Notably, the knockdown of IL‐6 in hippocampal microglia and IL‐6R in hippocampal astrocytes significantly improved astrocyte survival and alleviated anxiety‐ and depression‐like behaviors induced by CSDS." (PMID 39888279, 2025). "According to evidence, increasing levels of inflammatory markers such as IL-1β, IL-6, and TNF-α may be associated with depression." (PMID 40487411, 2025). "Assessing the interplay between IL-6 levels and treatment response could offer valuable insights as well into its potential and its limitations as a therapeutic target for depression." (PMID 39902492, 2025). "TENS can reduce serum IL-1β and IL-6 concentrations in patients with late-pregnancy depression." (PMID 40904577, 2025). "The findings indicated that the isolated mice displayed clear signs of anxiety and depression-like behaviors, along with increased levels of various cytokines (IL-1β, IL-6, and TNF-α) in the hippocampus and decreased levels of Sirt1, accompanied by elevated NF-κB p65 expression." (PMID 41317200, 2025). "Chronic inflammation has been shown to play a central role in the pathogenesis of various psychiatric disorders, particularly in the development of depression and anxiety, with inflammatory mediators (such as IL-6 and TNF-α) playing a crucial role in their onset and progression." (PMID 41144483, 2025). "Our results showed that vitamin D supplementation was associated with an increased GPx activity in both regimens, significantly reduced IL-6 levels in the bolus group, and improvements in anxiety and depression scores, particularly among patients receiving daily supplementation." (PMID 40429727, 2025). "One of the most well-studied pro-inflammatory cytokines in depression is interleukin-6 (IL-6)." (PMID 40004109, 2025). "Notably, IL-6 has become a potential biomarker for cancer-related depression, especially in patients with advanced or treatment-resistant disease." (PMID 41149069, 2025). "A positive correlation exists between elevated IL-6 levels and depressive symptoms, suggesting depression may accelerate tumor progression in part through enhancing IL-6 signaling." (PMID 41480347, 2025). "•IL-6 increases the 9-year social strain-to-depression link across assay methods." (PMID 41210298, 2025). "For example, elevated plasma levels of interleukin-6 (IL-6)—a ‘keystone’ cytokine involved with both pro- and anti-inflammatory signalling —are consistently reported in people with depression, but are also present in eating disorders, psychosis, and post-traumatic stress disorder (PTSD)." (PMID 41450979, 2025). "Elevated expression of tumor necrosis factor-α (TNF-α), interleukin-1β (IL-1β), interleukin-6 (IL-6), and nuclear factor kappa B (NF-κB) signaling have been identified in patients with depression and replicated in animal models of high-fat diet (HFD) and stress-induced behavioral despair." (PMID 40558565, 2025). "MiR-532-5p alleviates depression-like behaviors in CUMS-exposed mice by suppressing the expression of IL-6, interleukin-1 beta (IL-1β), TNF-α, and monocyte chemoattractant protein-1 through inhibition of the signal transducer and activator of transcription 3 pathway." (PMID 40949123, 2025). "The levels of IL-6 were found to be significantly associated with nonmotor symptoms, including psychosis, depression, anxiety, apathy, dopamine dysregulation syndrome, constipation, and lightheadedness on standing (LHON)." (PMID 40868280, 2025).
depression (continued). "Studies examining the relationships between depression and the inflammatory markers in peripheral blood revealed a positive correlation between depression and inflammatory markers such as C-reactive protein, IL-1, and IL-6." (PMID 40243556, 2025). "It is also possible that the suppression of IL-6, a pro-inflammatory cytokine, by filgotinib may have contributed to the improvement of depression, but this point awaits clarification in future studies." (PMID 39941545, 2025). "Potential mechanisms involve sleep-related inflammation: poor sleep quality correlates with elevated pro-inflammatory cytokines (e.g., IL-6 and CRP), which may disrupt neural circuits regulating mood, thereby increasing depression risk." (PMID 40218955, 2025). "Microglia generally serve a protective function; however, under pathological conditions, such as depression or neurodegenerative diseases, these cells become overactivated, leading to the release of pro-inflammatory cytokines, such as IL-6 and IL-8, and increased neuroinflammation." (PMID 40498007, 2025). "Inflammatory mediators, such as tumor necrosis factor-alpha (TNF-α) and interleukin-6 (IL-6), can reach brain tissue and influence the development of depression and sleep disorders by modulating synaptic transmission, neuronal excitability, neuronal survival, and synaptic plasticity." (PMID 40927014, 2025). "These genomic and neurobiological pathways might explain why IL-6 is the only inflammatory modifier with sufficient sensitivity to predict the early signs of depression." (PMID 41274868, 2025). "In conclusion, our results support a potential proinflammatory etiopathogenetic model for the risk of developing depressive symptoms in patients with pSS suggesting that IL-6 could be a predictor of pSS-related depression." (PMID 40822847, 2025). "Furthermore, IL‐6 released from activated microglia plays a crucial role in the development of depression by inducing astrocyte atrophy and apoptosis." (PMID 39888279, 2025). "Moreover, the relationship between genetic factors and inflammation is also supported by research examining the role of C-reactive protein (CRP) and interleukin-6 (IL-6) in depression." (PMID 40004109, 2025). "This suggests that evaluating IL-6 vis-à-vis fibrinogen and CRP may better capture nuanced pathways through which inflammation interacts with psychosocial factors to influence depression symptom risk." (PMID 41210298, 2025). "However, the cellular and molecular mechanisms by which elevated IL‐6 levels contribute to the progression of depression remain poorly understood." (PMID 39888279, 2025). "However, increased IL-6 and C-reactive protein (CRP) levels have been consistently associated with suicidal behaviour in people with depression and anxiety, independently of depression severity." (PMID 40420573, 2025). "Pro-inflammatory proteins, such as TNF-α, IL-1 and IL-6, are potent activators of the hypothalamic–pituitary–adrenal axis (HPA) and release of these proteins leads to hypersecretion of adrenal glucocorticoids which have been linked to depression." (PMID 39867847, 2025). "Overall, these findings indicate that knocking down IL‐6 in hippocampal microglia and IL‐6R in hippocampal astrocytes, along with inhibition of the IL‐6 trans‐signaling pathway using sgp130, significantly alleviates depression‐like behaviors and reduces astrocyte atrophy in CSDS mice." (PMID 39888279, 2025). "The findings suggest that IL-6 could be a predictor of pSS-related depression, potentially serving as a biomarker for this extraglandular manifestation and ESSPRI fatigue as a predictor for anxiety." (PMID 40822847, 2025). "Median (IQR) of IL-6 concentration in patients with depression was 2.8 (1.58-5.58) pg/mL in comparison to 1.50 (1.50-1.53) pg/mL in patients without depression, and 2.40 (1.50-5.60) pg/mL in patients with anxiety compared to 1.50 (1.50-2.00) pg/mL in patients without anxiety." (PMID 40822847, 2025).
depression (continued). "In addition, the IL‐6/IL‐6R pathway represents a potential target for depression treatment, offering valuable insights into depression therapy." (PMID 39888279, 2025). "One hypothesis suggests that gut dysbiosis may contribute to enhanced cytokines release (e.g., IL-1β, IL-6, TNF-α), resulting in a higher activation of the HPA axis and enhancing the risk of developing symptoms of anxiety and depression in IBD." (PMID 39870972, 2025). "Similar findings have been reported in previous studies showing that depression in chronic HBV-infected patients may be associated with immune dysregulation and increased inflammatory cytokines, such as IL-6, IL-8, TNF-α, and TGF-β." (PMID 41239311, 2025). "Future research examining level of depression and inflammatory protein concentrations in serum, saliva, cerebrospinal fluid and neuroimaging may assist in further extrapolating the relationship between TNF-α, IFN-γ, IL-6 and IL-10 and depression." (PMID 39867847, 2025). "Chronic inflammatory states, driven by depression, may lead to increased production of pro-inflammatory cytokines, such as interleukin-6 and tumor necrosis factor-alpha, which are known to damage retinal microvasculature." (PMID 40290656, 2025). "Pro-inflammatory activation of limbic system microglia is a known phenomenon in major depression, and this so-called state of low grade brain inflammation is systemically reflected by raised blood levels of proinflammatory cytokines (amongst which IL-6, 14)." (PMID 39867848, 2025). "In addition, exercise-induced IL-6 activates CREB via the PI3K/AKT pathway to decrease depressive disorder, primarily by activating BDNF signaling in the hippocampus." (PMID 40843259, 2025). "Similarly, anti-inflammatory drugs targeting cytokine pathways, such as IL-6 or TNF-α inhibitors, are being explored as adjunctive treatments for depressive disorders associated with chronic inflammation." (PMID 40002916, 2025). "SSRIs have an immunomodulatory effect in patients with depression by significantly reducing the peripheral pro-inflammatory cytokine markers of IL-6 and TNF-α, which may contribute to ameliorating the response to antidepressant drug treatment." (PMID 39050288, 2024). "Likewise, heightened levels of IL-1β, IL-6, IL-12, IL-18, TGF-β, and TNF-α are linked to AD, and importantly, patients diagnosed with both AD and depression demonstrate the highest levels of IL-6 and TNF-α in their circulatory system." (PMID 38903903, 2024). "We hypothesize that patients receiving either LLLT or MET would demonstrate superior improvement in terms of shoulder function, pain intensity, shoulder ROM, interleukin 6 (IL-6), depression, anxiety, and QoL compared to those receiving CTE." (PMID 38689290, 2024). "Those with high levels of TNF but not IL6 or CRP were associated with a greater presence of depression." (PMID 38175420, 2024). "Elevated levels of TNF, IL‐6, and IL‐1β in depression may result from dysfunction in the brain's anti‐inflammatory mechanisms, including the HPA axis and noradrenergic innervation." (PMID 38898740, 2024). "This is confirmed by our detection of increased serum IL-6, TNF-α, CRH, and CORT levels as well as decreased hippocampal BDNF expression in depression-like mice, these results are both caused by depression and in turn can exacerbate depression." (PMID 39494347, 2024). "Common pathogenetic pathways between psoriasis and depression, with the overproduction of cytokines such as IL-6, IL-17, and TNFa, could contribute to this phenomenon." (PMID 39518563, 2024). "While IL-6-receptor antagonists are expected to improve depression and mood in general in patients with a mood disorder, given that they counteract the neuroinflammation that IL-6 is likely to induce, they are still to be tested in patients with major depressive disorder." (PMID 38248262, 2024). "However, both the prolonged CUMS exposure and the LPS-induced depression model led to a significant reduction in IL-6 mRNA levels." (PMID 39273641, 2024).